PAF1 (PAF1 component of Paf1/RNA polymerase II complex)
Description:
Component of the PAF1 complex (PAF1C) which has multiple functions during transcription by RNA polymerase II and is implicated in regulation of development and maintenance of embryonic stem cell pluripotency. PAF1C associates with RNA polymerase II through interaction with POLR2A CTD non-phosphorylated and 'Ser-2'- and 'Ser-5'-phosphorylated forms and is involved in transcriptional elongation, acting both independently and synergistically with TCEA1 and in cooperation with the DSIF complex and HTATSF1. PAF1C is required for transcription of Hox and Wnt target genes. PAF1C is involved in hematopoiesis and stimulates transcriptional activity of KMT2A/MLL1; it promotes leukemogenesis through association with KMT2A/MLL1-rearranged oncoproteins, such as KMT2A/MLL1-MLLT3/AF9 and KMT2A/MLL1-MLLT1/ENL. PAF1C is involved in histone modifications such as ubiquitination of histone H2B and methylation on histone H3 'Lys-4' (H3K4me3). PAF1C recruits the RNF20/40 E3 ubiquitin-protein ligase complex and the E2 enzyme UBE2A or UBE2B to chromatin which mediate monoubiquitination of 'Lys-120' of histone H2B (H2BK120ub1); UB2A/B-mediated H2B ubiquitination is proposed to be coupled to transcription. PAF1C is involved in mRNA 3' end formation probably through association with cleavage and poly(A) factors. In case of infection by influenza A strain H3N2, PAF1C associates with viral NS1 protein, thereby regulating gene transcription. Connects PAF1C with the RNF20/40 E3 ubiquitin-protein ligase complex. Involved in polyadenylation of mRNA precursors. Has oncogenic activity in vivo and in vitro.
Synonyms: PD2; F23149_1; FLJ11123
Tractability: PROTAC: UniProt records ubiquitination sites on it; ubiquitination databases record sites on it; its protein half-life has been measured.
Gene: Protein-coding gene on chromosome 19 (39,385,629 to 39,391,154, reverse strand). Ensembl gene ENSG00000006712.
Subcellular location: Nucleus
Subcellular location (Human Protein Atlas): Nucleoplasm; Nucleoli fibrillar center; Vesicles
Pathways (Reactome):
Gene expression (Transcription): Formation of RNA Pol II elongation complex; RNA Polymerase II Pre-transcription Events; RNA Polymerase II Transcription Elongation
Chromatin organization: CHD1 and CHD2 subfamily
Disease: Dengue virus activates/modulates innate and adaptive immune responses
Metabolism of proteins: E3 ubiquitin ligases ubiquitinate target proteins
Gene Ontology:
Molecular function: protein binding; RNA polymerase II complex binding; chromatin binding
Biological process: mRNA 3'-end processing; negative regulation of myeloid cell differentiation; positive regulation of cell cycle G1/S phase transition; positive regulation of transcription by RNA polymerase II; protein localization to nucleus; transcription elongation by RNA polymerase II; cellular response to lipopolysaccharide; endodermal cell fate commitment; negative regulation of transcription by RNA polymerase II; stem cell population maintenance
Cellular component: Cdc73/Paf1 complex; cytoplasm; fibrillar center; membrane; nucleoplasm; nucleus
Genetic constraint (gnomAD): Loss-of-function variants: 31 observed, 70.17 expected, observed/expected ratio (o/e) 0.44, 90% interval 0.33 to 0.6. The upper end of that interval is the gene's LOEUF score, 0.6, which puts it in group 2 of 6, group 1 being the genes least tolerant of losing a copy. Missense variants: 435 observed, 719.33 expected, observed/expected ratio (o/e) 0.6, 90% interval 0.56 to 0.65. Synonymous variants: 256 observed, 250.85 expected, observed/expected ratio (o/e) 1.02, 90% interval 0.92 to 1.13.
Homologues: Orthologues: chimpanzee PAF1 (100% identical), macaque PAF1 (99% identical), mouse Paf1 (99% identical), rat Paf1 (98% identical), dog PAF1 (98% identical), rabbit PAF1 (97% identical), pig PAF1 (76% identical), tropical clawed frog paf1 (76% identical), zebrafish paf1 (53% identical), Drosophila melanogaster atms (49% identical), Caenorhabditis elegans pafo-1 (27% identical), Caenorhabditis elegans tag-343 (19% identical), and 1 more.
Diseases named in the same sentence as PAF1 in open-access papers:
PAF1 is named in the same sentence as 56 diseases in open-access papers, as found by Europe PMC text mining. Sharing a sentence is not in itself a finding about the gene and the disease. The quoted sentences say what the papers report.
pancreatic cancer (10 papers, 2009 to 2024). "Pancreatic differentiation 2 (PD2), also called PAF1 (RNA Polymerase II Associated Factor 1), is elevated in PC and regulates pancreatic cancer stem cells (PCSCs)." (PMID 36180487, 2022). "PAF1 is highly expressed in various cancers, such as pancreatic cancer and lung cancer, and is associated with tumor metastasis, minimal differentiation, therapeutic resistance, and poor prognosis." (PMID 32471508, 2020). "In poorly differentiated pancreatic cancer, elevated PAF1 levels were associated with downregulation of proteasomal degradation." (PMID 31598166, 2019). "In conclusion, our studies indicate loss of PD2/Paf1 expression during acinar transdifferentiation in pancreatic cancer initiation and PD2/Paf1 mediated regulation of lineage specific markers." (PMID 24947474, 2014). "Since pancreatic cancer is widely associated with loss of cell cycle due to deregulated expression of cyclins and cdks (cyclin dependent kinases), hence we anticipate that aberrant PD2/Paf1 might have a role in pancreatic cancer pathogenesis." (PMID 24947474, 2014). "The PAF1 gene is located in the 19q13.2 amplicon locus and was first identified in poorly differentiated pancreatic cancer cell lines (expressed 30-fold greater than that of well-differentiated cancer cell lines)." (PMID 32471508, 2020). "PD2/Paf1 expression appears to be retained at a low level in the ductal cells of acinar origin and subsequently increases during the later stages of pancreatic cancer progression." (PMID 24947474, 2014). "Next, we investigated the expression of the PD2/Paf1 protein during pancreatic cancer progression by immunofluorescent staining of pancreatic tissues of the KC mice." (PMID 24947474, 2014). "Recently, we demonstrated that PD2/Paf1 also regulates histone methylation and chromatin remodeling in pancreatic cancer cells." (PMID 24947474, 2014). "The PD2/Paf1 subunit which constitutes the core of this complex, merits particular attention as it is overexpressed in poorly-differentiated pancreatic cancer cell lines as well as in mouse xenografts." (PMID 24947474, 2014). "In this study we demonstrate for the first time a unique role of this novel protein PD2/Paf1 in pancreatic acinar to ductal metaplasia during murine pancreatic cancer progression." (PMID 24947474, 2014). "Our recent study revealed that PD2/Paf1 plays an important role in the maintenance of self-renewal and drug resistance of pancreatic cancer stem cells." (PMID 24947474, 2014). "Notably, PAF1 contributes to the maintenance of pancreatic cancer stemness via its interaction with PHF5A and DDX3, but not through the typical PAF1 complex, Pol II pause release, or stable β-catenin." (PMID 38182897, 2024). "Since PD2/Paf1 has been shown to regulate H3K4 methylation status in pancreatic cancer cells, this function might account for the role of PD2/Paf1 in maintenance of acinar cell lineage." (PMID 24947474, 2014). "In this study, we investigated whether PAF1 is required for the YAP1-mediated PDAC development and whether CA3 and verteporfin, small molecule inhibitors of YAP1/TEAD transcriptional activity, diminish pancreatic cancer (PC) cell growth by targeting the PAF1/YAP1 axis." (PMID 36180487, 2022). "The elevated expression of PD2/Paf1 in pancreatic cancer may suggest that it plays a biphasic role during pancreatic cancer progression; its initial downregulation allows acinar cell de-differentiation and in later stages its elevated expression favors pancreatic tumor progression." (PMID 24947474, 2014). "In pancreatic cancer cells, PD2/Paf1, plays a role in cell cycle regulation by modulating expression of cyclins A1, A2, D1, E1, B1, and Cdk1." (PMID 24947474, 2014). "Inspired by the expressional and functional significance of PD2/Paf1 in various pancreatic cancer cells, we sought to determine the expression pattern of PD2/Paf1 in Pdx1-Cre; Kras G12D (KC) spontaneous mouse model of PC." (PMID 24947474, 2014).
pancreatic cancer (continued). "In murine pancreatic cancer progression models, however, PD2/Paf1 accumulated in the neoplastic ductal cells." (PMID 24947474, 2014). "PD2/Paf1, the main PAF subunit, is overexpressed in the poorly differentiated pancreatic cancer cell line Panc1 due to amplification of the 19q13 locus." (PMID 24947474, 2014). "ALDOA and PAF1 have recently been described as oncogenes in PDAC, whereas ENO1, RALGDS, TRIP10, and FLNA are known to mediate pancreatic cancer cell proliferation, survival and migration." (PMID 32029502, 2020).
acute myeloid leukemia (4 papers, 2016 to 2023). Acute myeloid leukemia (AML) is a group of neoplasms arising from precursor cells committed to the myeloid cell-line differentiation. "Moreover, ChIP-seq analyses in human acute myeloid leukemia THP1 cells showed that PAF1 occupancy generally overlaps with the promoter-proximal RNAPII peaks whereas Ctr9 occupancy does not, reinforcing the PAFc independent functions of Ctr9." (PMID 27829357, 2016).
breast carcinoma (4 papers, 2020 to 2024). "Likewise, ERK5 in a complex with cofilin, an actin-severing protein required for actin cytoskeleton reorganization, facilitated PAF1 recruitment at genomic loci to permit estrogen-induced expresion of genes associated with breast cancer cell proliferation." (PMID 32023819, 2020). "Interestingly, our results also showed that UBR5 can not only down-regulate the expression of the CDC73 in breast cancer cells, but also additional PAF1C subunits PAF1, CTR9, and LEO1." (PMID 35551175, 2022).
pancreatic ductal adenocarcinoma (4 papers, 2014 to 2023). An infiltrating adenocarcinoma that arises from the epithelial cells of the pancreas. "In addition, SUMOylation of PAF1/PD2 has been demonstrated to induce radio-resistance in pancreatic ductal adenocarcinoma." (PMID 37886949, 2023). "Interestingly, metaplastic ducts in chronic pancreatitis, PanINs, and pancreatic ductal adenocarcinoma (PDAC) showed a clear co-expression of PAF1 and YAP1." (PMID 36180487, 2022).
colon cancer (3 papers, 2020 to 2025). "In this study, we investigated the transcriptional mechanism underlying the control of colon cancer stemness by stable β-catenin through the NELF and PAF1 complexes." (PMID 38182897, 2024). "Since PAF1 is highly expressed in CC tissue and PAF1 promotes the release of Pol II on the IER5 promoter in colon cancer cells, we decided to study further the relationship between PAF1 and IER5 in CC cells." (PMID 32471508, 2020). "Additionally, DSIF and PAF1 complexes acted as transcriptional platforms that integrated and funneled both tumor-suppressive and oncogenic signals into the expression of genes that control colon cancer stemness." (PMID 40399276, 2025). "Moreover, PAF1 knockdown decreased the expression levels of the genes such as LGR5, ID1, ID3, CD44v9, CD133, BMI1, RNF43, EPHB2, SOX9, and ASCL2, which are critical for inducing colon cancer stemness and its markers." (PMID 38182897, 2024).
glioblastoma (3 papers, 2016 to 2022). The most malignant astrocytic tumor (WHO grade IV). "It has been shown that the PINT87aa peptide interacts with PAF1, keeps the PAF1 complex on the target gene promoter, and regulates the formation of the PAF1/Pol II complex, thus controlling its downstream effects in the progression of several cancer types, including glioblastoma, BC, HCC, and GC." (PMID 35223470, 2022).
ovarian carcinoma (3 papers, 2017 to 2025). A malignant neoplasm originating from the surface ovarian epithelium. "The C-terminal region of BRCA2 apparently necessary for PAF1 recruitment is often deleted in truncating mutations associated with breast and ovarian cancer, suggesting its functional significance in tumor suppression." (PMID 29386125, 2018). "We found that the expression of BANF1, CDK2AP2, DDT, LRIG1, MRPL4, and S100A13 was upregulated in ovarian cancer samples, and the expression of EPS8, NUCB2, PAF1, PMP22, RABGAP1L, and USO1 was upregulated in normal samples." (PMID 41000388, 2025).
leukaemia (2 papers, 2023 to 2025). "Here, the authors show that MLL-AF4 cooperates with PAF1 and FACT at enhancers to promote high-density interactions with oncogene promoters in leukemia." (PMID 37626123, 2023). "PAF1 and FACT are highly enriched at enhancers bound by MLL-AF4 in MLLr leukemias and help create aberrant regions of high-density promoter interactions." (PMID 37626123, 2023). "Together, these data suggest that PAF1 and FACT may have a general role in enhancer activity in MLL-AF4 leukemia cells, including enhancer-promoter contact, but they have a particularly strong impact on MLL-AF4-bound enhancers." (PMID 37626123, 2023). "Thus, while PAF1 may have a particularly central role in transcription in MLL-AF4 leukemias, this is not universal and may be a consequence of the activity and multivalent interactions of the MLL-AF4 complex." (PMID 37626123, 2023). "Taken together, this suggests that the role of PAF1 in driving enhancer activity is not crucial in all disease contexts and may be unique to MLL-AF4-driven leukemias." (PMID 37626123, 2023).
multiple myeloma (2 papers, 2023 to 2025). "The SEI1 directly interacts with the enhancer factors CREB‐binding protein (CBP)/p300 and RNA polymerase II (pol II)‐associated factor 1 (PAF1) complex, promoting transcriptional activity and leading to upregulation of programmed death ligand‐1 (PD‐L1) and immune escape in myeloma." (PMID 40135791, 2025). "Further experiments confirmed that knocking down the expression of PAF1 in myeloma cells significantly suppressed the expression of PD‐L1 induced by melphalan or bortezomib." (PMID 40135791, 2025). "Our results confirmed the presence of PAF1, CDC73, or p300 in the immunoprecipitates, indicating the existence of the SEI1/CBP/p300/PAF1 complex in myeloma cells." (PMID 40135791, 2025). "The elevated expression of SEI1 directly interacts with the CBP/p300 and PAF1 transcriptional regulatory complexes to promote PD‐L1 expression, resulting in immune evasion in myeloma cells." (PMID 40135791, 2025). "This is in contrast to the dramatic reduction in transcription produced by PAF1 degradation in SEM (MLL-AF4 ALL) cells but matches the much weaker effect we observed in MM1.S (multiple myeloma) cells." (PMID 37626123, 2023). "We found that PAF1 binds at both typical enhancers and SEs in the multiple myeloma cell line MM1.S, for example, at the CCND2 locus, suggesting it may also have a functional role at enhancers in this disease context." (PMID 37626123, 2023). "To investigate the presence of the endogenous SEI1/CBP/p300/PAF1 complex in myeloma cells, we performed immunoprecipitation assays using anti‐SEI1, PAF1, CDC73, or p300 antibodies on myeloma cell lysates." (PMID 40135791, 2025). "In order to test the contribution of PAF1 in enhancer activity beyond MLL-AF4 enhancers, we investigated its role in multiple myeloma, which is known to be driven by oncogenic enhancer activity." (PMID 37626123, 2023).
prostate carcinoma (2 papers, 2016 to 2021). A carcinoma that arises from epithelial cells of the prostate gland. "Nuclear extracts were prepared from pooled prostate cancer vs. non-tumor adjacent tissues, then incubated with whole IgG control or PAF1 antibody, which resulted in moderate PAF1 depletion." (PMID 34732721, 2021).
autism (1 paper, 2022). Persistent deficits in social interaction and communication and interaction as well as a markedly restricted repertoire of activity and interest as well as repetitive patterns of behavior. "PAF1 complex was also reported to has mutations associated with autism, suggesting a model of potential interplay among HCF-1, PAF1 and SETD5 proposed in our study may be applicable in the onset/development of certain mental diseases." (PMID 34853439, 2022).
benign prostatic hyperplasia (1 paper, 2021). A non-cancerous nodular enlargement of the prostate gland. "We also performed the transcriptional recycling assay using nuclear extract of non-cancerous BPH1, a human benign prostatic hyperplasia cell line that expressed PAF1 at a lower level than LNCaP-abl." (PMID 34732721, 2021).
chronic myelogenous leukemia (1 paper, 2023). "One study in K562 (chronic myelogenous leukemia) cells identified distinct requirements for different PAF1C components in stimulating RNAPII activity, with degradation of the PAF1 subunit only weakly affecting RNA synthesis." (PMID 37626123, 2023).
chronic pancreatitis (1 paper, 2022). A chronic inflammatory process causing damage and fibrosis of the pancreatic parenchyma. "PAF1 expression was gradually elevated from chronic pancreatitis to PDAC." (PMID 36180487, 2022).
gastric cancer (1 paper, 2015). A primary or metastatic malignant neoplasm involving the stomach. "The cooperation of Paf1 and Scc2 could have wider implications in humans where the Paf1 complex is overexpressed in a wide range of cancers including prostate, breast, renal, and gastric cancers." (PMID 26176819, 2015).
malignant glioma (1 paper, 2021). A grade III or grade IV glioma arising from the central nervous system. "PINT87aa level was significantly downregulated in tumors and repressed the transcriptional extension of multiple oncogenes by binding to the polymerase-related factor complex gene PAF1, consequently alleviating the occurrence and development of malignant gliomas." (PMID 34869349, 2021).
pancreatic adenocarcinoma (1 paper, 2022). "First, we performed a cBioportal analysis of the correlation of PAF1 with YAP1 in the pancreatic adenocarcinoma (QCMG, Nature 2016) dataset." (PMID 36180487, 2022).
pancreatitis (1 paper, 2022). Inflammation of the pancreas. "We next focused on examining the expressional patterns of PAF1, YAP1, and TEAD1 in cerulein-induced wild-type (WT) and KrasG12D, Pdx-1 Cre (KC) pancreatitis mouse models." (PMID 36180487, 2022).
prostate tumors (1 paper, 2021). "Prostate tumors exhibited enhanced transcriptional recycling, which was attenuated by antibody-based PAF1 depletion." (PMID 34732721, 2021). "Interestingly, IHC analysis revealed significant over-expression of PAF1 in prostate tumor samples relative to both NAT and normal prostate tissue controls." (PMID 34732721, 2021). "In conclusion, prostate tumors exhibit higher rates of RNA Pol II transcriptional recycling relative to paired NAT, and this effect is at least partially PAF1-dependent." (PMID 34732721, 2021). "Significantly, PAF1 is elevated in prostate tumors and required for the higher transcription recycling detected in prostate tumors compared with adjacent non-tumor prostate tissues." (PMID 34732721, 2021).
Wilms tumor (1 paper, 2018). An embryonal neoplasm characterized by the presence of epithelial, mesenchymal, and blastema components. "In particular, PAF1 is involved in pancreatic and ovarian cancer, and CTR9 is involved in Wilms tumor and breast cancer." (PMID 30228257, 2018).